FOXB1 (forkhead box B1)
Description:
Transcription factor expressed by neural progenitor cells in specific regions of the embryonic neuroepithelium. Essential for the mammillary nuclei maintenance. Negatively regulates the proliferation of oligodendrocyte progenitors and promotes oligodendrocyte maturation. Also expressed in mammary glands, plays a role in lactation, controls development of mammary glands and the inferior colliculi of the midbrain in the central nervous system that regulates the milk-ejection reflex.
Synonyms: FKH5; HFKH-5
Tractability: No criterion of Open Targets' tractability assessment is met for any kind of drug.
Gene: Protein-coding gene on chromosome 15 (60,004,234 to 60,061,730, forward strand). Ensembl gene ENSG00000171956.
Subcellular location: Nucleus
Subcellular location (Human Protein Atlas): Mitochondria; Nucleoplasm
Gene Ontology:
Molecular function: protein binding; sequence-specific double-stranded DNA binding; DNA-binding transcription factor activity, RNA polymerase II-specific; RNA polymerase II cis-regulatory region sequence-specific DNA binding; sequence-specific DNA binding; DNA-binding transcription factor activity
Biological process: anatomical structure morphogenesis; axon target recognition; cell differentiation; cell migration in diencephalon; epithelial cell differentiation involved in mammary gland alveolus development; floor plate development; hypothalamus cell migration; inferior colliculus development; lactation; mammary gland lobule development; mammillary body development; mammillothalamic axonal tract development; midbrain development; negative regulation of neuron apoptotic process; regulation of transcription by RNA polymerase II; somitogenesis; telencephalon cell migration; visual learning; regulation of DNA-templated transcription; spinal cord development; thalamus development; urogenital system development
Cellular component: chromatin; nucleus
Genetic constraint (gnomAD): Loss-of-function variants: 6 observed, 17.18 expected, observed/expected ratio (o/e) 0.35, 90% interval 0.19 to 0.69. The upper end of that interval is the gene's LOEUF score, 0.69, which puts it in group 2 of 6, group 1 being the genes least tolerant of losing a copy. Missense variants: 419 observed, 453.4 expected, observed/expected ratio (o/e) 0.92, 90% interval 0.85 to 1. Synonymous variants: 213 observed, 212.03 expected, observed/expected ratio (o/e) 1, 90% interval 0.9 to 1.12.
Homologues: Orthologues: chimpanzee FOXB1 (100% identical), macaque FOXB1 (100% identical), rat Foxb1 (100% identical), dog FOXB1 (99% identical), mouse Foxb1 (99% identical), pig FOXB1 (99% identical), guinea pig FOXB1 (97% identical), tropical clawed frog foxb1 (86% identical), zebrafish foxb1a (80% identical), zebrafish foxb1b (73% identical), Drosophila melanogaster fd96Cb (35% identical). Paralogues in human: FOXB2 (58% identical), FOXD1 (31% identical), FOXD2 (31% identical), FOXA2 (31% identical), FOXC2 (31% identical), FOXC1 (30% identical), FOXE1 (30% identical), FOXA1 (28% identical), FOXD4 (28% identical), FOXA3 (27% identical), FOXD3 (27% identical), FOXD4L1 (27% identical), and 29 more.
Diseases named in the same sentence as FOXB1 in open-access papers:
FOXB1 is named in the same sentence as 17 diseases in open-access papers, as found by Europe PMC text mining. Sharing a sentence is not in itself a finding about the gene and the disease. The quoted sentences say what the papers report.
Anxiety (1 paper, 2022). Intense feelings of nervousness, tension, or panic often arise in response to interpersonal stresses. "When tested in the elevated plus maze, St8sia2−/− mice in cohort 2 showed signs of reduced anxiety that were fully reproduced by Foxb1-Cre;St8sia2f/f and, for the time spent in the closed relative to the open arm, also by Foxb1-Cre;Emx1-Cre;St8sia2f/f mice." (PMID 35115485, 2022).
autism (1 paper, 2019). Persistent deficits in social interaction and communication and interaction as well as a markedly restricted repertoire of activity and interest as well as repetitive patterns of behavior. "For example, ARX is required for normal telencephalic development and is associated with syndromic autism and other neurodevelopmental disorders, while EMX1 and FOXB1 also play important roles in neural development." (PMID 31893020, 2019).
Bradycardia (1 paper, 2024). A slower than normal heart rate (in adults, slower than 60 beats per minute). "The measurement of cardiovascular parameters in a group of 8 Foxb1-Cre mice revealed a sudden onset of bradycardia in three mice (106/21–10, 34/21–7, 34/21–10), immediately after starting the optogenetic activation." (PMID 38300670, 2024).
inflammatory bowel disease (1 paper, 2020). A spectrum of small and large bowel inflammatory diseases of unknown etiology. "Unbiased genome-wide association study analysis also associated new phenotypes with TFs in the constructed Th17 network, such as the function of FOXB1 in regulating inflammatory bowel disease-related genes." (PMID 32717640, 2020).
lung carcinoma (1 paper, 2025). "Consequently, we propose that KCNA7 and FOXB1 function as core genes regulating lung cancer recurrence and are associated with poor survival outcomes in NSCLC patients." (PMID 40568194, 2025). "Validation at the single-cell level indicated that the FOXI1, FOXB1, and KCNA7 genes were linked to lung cancer progression." (PMID 40568194, 2025). "We further explored the effects of KCNA7 and FOXB1 on clinical traits in lung cancer patients." (PMID 40568194, 2025). "Our findings identify an important link to lung cancer development and highlight KCNA7, FOXI1, and FOXB1 as marker genes for CXCL1 cancer subgroups relevant to clinical prognosis." (PMID 40568194, 2025). "Following transcriptomic and single-cell histological analyses, we established that the highly expressed transcription factors FOXI1, FOXB1, and KCNA7 promote lung cancer development and are primarily involved in cellular processes including proliferation, migration, and invasion." (PMID 40568194, 2025). "Collectively, these results suggest that FOXB1 and KCNA7 may serve as biomarkers for prognostic evaluation in lung cancer and provide a novel theoretical foundation for clinical treatment strategies." (PMID 40568194, 2025). "The results revealed that the expression levels of KCNA7 and FOXB1 were significantly higher in patients with recurrence lung cancer compared to those in the non-recurrence group." (PMID 40568194, 2025).
cancer (3 papers, 2014 to 2025). A tumor composed of atypical neoplastic, often pleomorphic cells that invade other tissues.
tumor (2 papers, 2021 to 2025). "The tumor tissues displayed an enriched expression of transcription factors (e.g., Dlx2, Gbx2, Foxb1, and Nkx2.2) critical for brain development, tanycyte markers (e.g., Ptprz1, Fabp7, Crym, and Gja1), and differentiation markers (e.g., Dcx, Olig1, and Cspg5)." (PMID 33863883, 2021).
FOXB1 also shares sentences with these, for which no sentence is quoted: infection (2 papers); asthma (1); breast tumor (1); co-infection (1); Cognitive impairment (1); colorectal cancer (1); inflammation (1); influenza (1); melanoma (1); neurodevelopmental disorder (1).